AKR1E2 (aldo-keto reductase family 1 member E2)
Description:
Catalyzes the NADPH-dependent reduction of 1,5-anhydro-D-fructose (AF) to 1,5-anhydro-D-glucitol (By similarity). Has low NADPH-dependent reductase activity towards 9,10-phenanthrenequinone (in vitro).
Synonyms: htAKR; hTSP; AKR1CL2; AKRDC1; MGC10612; HTSP1; LoopADR; TAKR
Tractability: PROTAC: ubiquitination databases record sites on it.
Gene: Protein-coding gene on chromosome 10 (4,786,629 to 4,848,062, forward strand). Ensembl gene ENSG00000165568.
Subcellular location: Cytoplasm
Subcellular location (Human Protein Atlas): Golgi apparatus; Nucleoplasm; Cytosol
Pathways (Reactome):
Metabolism: Glycogen breakdown (glycogenolysis)
Gene Ontology:
Molecular function: 1,5-anhydro-D-fructose reductase activity; oxidoreductase activity; aldose reductase (NADPH) activity; oxidoreductase activity, acting on the CH-OH group of donors, NAD or NADP as acceptor
Biological process: glycogen catabolic process
Cellular component: cytosol; cytoplasm
Genetic constraint (gnomAD): Loss-of-function variants: 43 observed, 42.6 expected, observed/expected ratio (o/e) 1.01, 90% interval 0.79 to 1.3. The upper end of that interval is the gene's LOEUF score, 1.3, which puts it in group 5 of 6, group 1 being the genes least tolerant of losing a copy. Missense variants: 423 observed, 412.64 expected, observed/expected ratio (o/e) 1.03, 90% interval 0.95 to 1.11. Synonymous variants: 121 observed, 144.85 expected, observed/expected ratio (o/e) 0.84, 90% interval 0.72 to 0.97.
Homologues: Orthologues: chimpanzee AKR1E2 (99% identical), macaque AKR1E2 (94% identical), guinea pig AKR1E2 (72% identical), pig AKR1E2 (71% identical), mouse Akr1e1 (70% identical), dog AKR1E2 (70% identical), rat Akr1e2 (69% identical), rabbit AKR1E2 (53% identical), Drosophila melanogaster Akr1B (51% identical), Caenorhabditis elegans Y39G8B.1 (38% identical), Caenorhabditis elegans Y39G8B.2 (31% identical), Caenorhabditis elegans C01G5.5 (26% identical), and 2 more. Paralogues in human: AKR1B1 (56% identical), AKR1B10 (55% identical), AKR1B15 (55% identical), AKR1D1 (45% identical), AKR1C4 (45% identical), AKR1C8 (44% identical), AKR1C1 (43% identical), AKR1C2 (43% identical), AKR1C3 (43% identical), AKR1A1 (41% identical), KCNAB1 (24% identical), KCNAB2 (24% identical), and 4 more.
Diseases named in the same sentence as AKR1E2 in open-access papers:
AKR1E2 is named in the same sentence as 2 diseases in open-access papers, as found by Europe PMC text mining. Sharing a sentence is not in itself a finding about the gene and the disease.
AKR1E2 shares sentences with these, for which no sentence is quoted: retinoblastoma (1 paper); tumor (1).